DAB2 (DAB adaptor protein 2)
Diseases named in the same sentence as DAB2 in open-access papers (continued):
Sharing a sentence is not in itself a finding about the gene and the disease.
tumor (continued). "The current finding that estrogen, progesterone, and prolactin induce expression of Dab2, a growth and tumor suppressor, may represent a feedback mechanism for growth control." (PMID 25360623, 2014). "Interestingly, in our samples DAB2 was equally expressed in the normal and in the tumor condition, differently from what was observed in other tumors where it is significantly down-regulated." (PMID 24194935, 2013). "Moreover, DAB2 plays an important regulatory role in cellular differentiation and acts as a tumor suppressor, at least in part, by stabilizing the beta-catenin degradation complex, thus negatively regulating the Wnt signaling pathway." (PMID 24194935, 2013). "The high frequency of epigenetic inactivation of DAB2 in NPC has led to the hypothesis that DAB2 might be a tumour suppressor gene in this cancer." (PMID 20525238, 2010). "The differential expression patterns pointed to a possible tumour suppressor role of DAB2 in NPC." (PMID 20525238, 2010). "Our functional studies support the putative tumour suppressor effect of DAB2 in NPC cells." (PMID 20525238, 2010). "The frequent down-regulation of DAB2 in NPC implied that it might be a tumour suppressor gene involved in NPC pathogenesis." (PMID 20525238, 2010). "In keeping with this hypothesis, we demonstrated that exogenous expression of DAB2 suppressed NPC tumour growth in vitro as demonstrated by cell proliferation assay, and reduced the anchorage-dependent colony formation." (PMID 20525238, 2010). "DAB2, also known as Disabled-2, is a clathrin and cargo binding endocytic adaptor protein recognized for its diverse roles in signaling pathways involved in cell differentiation, proliferation, migration, tumor suppression, and other fundamental cellular homeostatic mechanisms." (PMID 39239526, 2024). "As the dysregulation of immunoproteasomes and chemokines promotes immune evasion of cancer cells, suppression of MAF, GATA6, and DAB2 may contribute to the maintenance of the tumor microenvironment, which is advantageous for EMT and immune escape in the early stages of tumorigenesis." (PMID 37779141, 2023). "However, this study showed the opposite role for DAB2 during tumor progression." (PMID 31968685, 2020). "Disabled-2 (DAB2) is a clathrin and cargo binding endocytic adaptor protein recognized for its multifaceted roles in signaling pathways involved in cellular differentiation, proliferation, migration, tumor suppression, and other fundamental homeostatic cellular mechanisms." (PMID 33178208, 2020). "Thus, the DAB2-related pathway in the tumor microenvironment may be involved in disease progression." (PMID 31968685, 2020). "DAB2 may exert numerous roles in tumor alteration and progression." (PMID 31968685, 2020). "Our findings support that DAB2 may have a tumor-suppressive function in EBVaGC." (PMID 32025216, 2020). "DAB2 might exert the tumour suppression function by inhibiting c-Fos expression in NPC." (PMID 20525238, 2010). "The expression levels of the genes CD36, CXCL14, DAB2, MARCKS, ENPEP, and TIMP1 in normal, tumor, and metastatic tissues were analyzed using various statistical methods." (PMID 40565366, 2025). "The low expression of DAB2 in HER2-, ER-, and TNBC tumors further highlights its potential role as a tumor suppressor in aggressive BC subtypes." (PMID 40565366, 2025). "However, recent studies have found that DAB2+ macrophages may promote tumor development." (PMID 39239526, 2024). "On the other hand, among the tumor-specific 63 ceRNAs, GALNT7, KLF9, and DAB2, which are common to all three tumor tissues and were significantly expressed in at least two tissues, were found in this core miRNA:ceRNA cluster." (PMID 38627780, 2024). "These cancer research findings are consistent with our observations, suggesting that DAB2 enhances EVT’s ability to modify vascular structures, akin to facilitating tumor cell migration and invasion." (PMID 38613672, 2024).
tumor (continued). "FAP+ CAFs had the strongest spatial co-localization with DAB2+ TAMs in HCC, and DAB2+ TAMs had the highest proportion among all macrophages at the tumor border slides." (PMID 39239526, 2024). "Most strikingly, our analysis revealed a seven-gene drug-tolerant signature in all four drug-tolerant cell lines, irrespective of chemotherapeutic treatment, parental cell line and tumour subgroup—LTBP1, MAP1A, MBNL2, LGALS1, PNRC1, DAB2 and PLAAT3." (PMID 36831428, 2023). "In addition, the finding that SCFAs attenuate Ras signaling in vivo, in part, by up-regulating the expression of human disabled 2 (DAB2), a tumor suppressor of the Ras and Wnt pathways, suggests that SCFAs may also impact FGFR2 and Hippo signaling in tumor development." (PMID 37432606, 2023). "In early tumorigenesis, DAB2 promotes the TGF β/SMAD pathway, supressing tumor growth and promoting epithelial mesenchymal transition." (PMID 37510211, 2023). "The model mice with SCFAs showed fewer tumor nodules and increased expression of disabled homolog 2 (DAB2), a tumor suppressor." (PMID 36483296, 2022). "As an effect, Dab2-knockdown DCs were more effective in stimulating antigen-specific cytotoxic CD8 T cells responses in mice and enhanced the efficacy of DC-based tumor immunotherapy than wild-type DCs." (PMID 33178208, 2020). "Similar profile is seen in genes expressed in HCCN vs. HCV+HCC (tumor state): PCNA-AS1, ROBO1, DAB2, and IFI30 (lower part)." (PMID 28938650, 2017). "hnRNP E1 was later described to be modulated in TGFβ-induced EMT and tumor metastasis and was found to affect translation of ILEI and Dab2 mRNAs." (PMID 23715860, 2013). "To explore the mechanism for tumour suppression by DAB2 in NPC, we studied the effect of DAB2 on serum-induced MAP kinase signalling in NPC cells C666-1." (PMID 20525238, 2010). "In the morphologically normal epithelia immediately adjacent to tumor areas, both GATA6 and Dab2 are positive." (PMID 19649254, 2009). "Additionally, coincident DAB2 and active-YAP1 upregulation was observed in GC tumor tissues and indicated a poor prognosis, indicating that elevated DAB2 and active-YAP1 expression levels served as predictive biomarkers for GC." (PMID 38481347, 2024). "Finally, to evaluate the clinical significance of FAP and DAB2, we further included 90 HCC tumor boundary samples for IHC staining, in which FAP+ CAFs and DAB2+ TAMs enriched around the tumor core." (PMID 39239526, 2024). "In HCC ST slides from immunotherapy-non-responsive patients, FAP and DAB2 were found to be concentrated at the tumor border, creating a barrier that effectively blocked the infiltration of T/B cells." (PMID 39239526, 2024). "Hence, we believe that the complimentary approach used in our study contributes to the knowledge of the role of DAB2 in CRC and supports previous findings on its tumor suppressor role." (PMID 37510211, 2023). "The role of DAB2 is that expression in CAFs promotes EMT of tumor cells, and induces tumor migration and invasion, resulting in the accumulation of cancer cells that are beneficial to the tumor microenvironment." (PMID 31968685, 2020). "In these predicted target genes, DAB2 is considered a candidate tumor suppressor gene for its absent and reduced expression in various tumors." (PMID 26769181, 2016). "We studied the expression of DAB2 in NPC cell lines, xenografts and primary tumour samples." (PMID 20525238, 2010). "Notably, DAB2+ TAMs enriched in HCC, exhibiting significant spatial co-localization with FAP+ CAF in tumor border and may participate in shaping the TME." (PMID 39239526, 2024).
tumor (continued). "DAB2 downregulation, which results in suppressing R-Smad/canonical TGF-β signaling, not only correlates with poor prognosis but also fundamentally alters the TGF-β response from a tumor suppressor into a potent promoter of migration, anchorage-independent growth, and in vivo tumor growth." (PMID 38675493, 2024). "Therefore, reducing the infiltration of DAB2+ TAMs or SPP1+ TAMs at the tumor border and blocking their cellular communication with FAP+ CAFs may be another way to enhance anti-tumor immunity." (PMID 39239526, 2024). "The tumor suppressor role of DAB2 in CRC might be related to the activity of DAB2 in the uptake of vitamin D receptor binding protein (DBP) in colon and prostate cells, a topic that concerns the role of vitamin D as a tumor suppressor in the colon, and other organs." (PMID 37510211, 2023). "DAB adaptor protein 2 (DAB2), also known as disabled 2 (Dab2) and differentially expressed in the ovarian carcinoma 2 (DOC-2), is a gene that codes the clathrin-based transmembrane protein (CLASP) to regulate endocytosis, promote embryonic development and inhibit the growth of tumor cells." (PMID 37510211, 2023). "Interestingly, PD-L inhibitors, which allow T-cell mediated death of tumour cells, further reduced the number of lung metastases in DAB2 KO mice but not WT mice." (PMID 36614139, 2022). "The molecular basis for the tumor suppressive function of Dab2 are currently unclear since its suppression of Ras/MAPK signaling or its impact on cell adhesion, cell migration and epithelial organization could all be imagined to influence tumor growth." (PMID 31671891, 2019). "Comparison of the reduction rate of tumor weight in LK and SPC cells with X-ray irradiation (74.4% VS 43.31%, P < 0.05), demonstrates that LK cells with hypermethylation of the Dab2 gene promoter are more sensitive to X-ray treatment than SPC cells with hypomethylation of the Dab2 gene promoter." (PMID 30547821, 2018). "Disabled-2 (DAB2) is a multifunctional adapter protein with tumor suppressor activity, which may act as a potent negative regulator of multiple signaling pathways, including the ERK, Wnt/β-catenin, and TGF-β pathways." (PMID 27036032, 2016). "Moreover, downregulation of DAB2 could enable TGF-β-mediated cell motility and tumor growth in vivo." (PMID 26769181, 2016). "Additionally, the staining intensity of FAP and DAB2 also exhibited a significant positive correlation with tumor size and patient serum AFP concentration (Spearman correlation analysis, P < 0.0001), suggesting their potential as indicators of tumor progression in clinical practice." (PMID 39239526, 2024). "Furthermore, as reported in other tumors types, upregulation of DAB2, RND3, TMEM97, CSE1L, MYO1C, and PTPRK have been shown to suppress or functionally redistribute E-cadherin expression in cancer cells, resulting in EMT, increased invasion, advanced tumor stage and poor patient survival." (PMID 27863424, 2016).
cancer (51 papers, 2005 to 2025). A tumor composed of atypical neoplastic, often pleomorphic cells that invade other tissues. "Using immunofluorescence, we found DAB2 to co-localize with CD68 macrophage marker in both the cancer associated stroma and within epithelial areas of HGSOC tissue." (PMID 37815603, 2023). "Previous studies demonstrated that low DAB2 protein expression is associated with poor patient prognosis in patients with cancers of the lung, bladder and esophagus." (PMID 37815603, 2023). "The majority of cancer tissue have either a complete loss or significant reduction in DAB2 expression which has been associated with malignant transformation of cells." (PMID 36614139, 2022). "A relationship between loss of DAB2 expression and promoter methylation status has been observed in cancers of the lung, nasopharynx, head and neck, vulva and liver." (PMID 36614139, 2022). "Disabled-2 (Dab2) is a multifunctional scaffold protein frequently downregulated in cancer that has been linked to the process of EMT." (PMID 31101868, 2019). "Our research reveals that the promoter hypermethylation of Dab2 is an important factors for the loss expression of Dab2 in human cancers tissues (OR = 24.45, P < 0.001)." (PMID 24772157, 2014). "The results indicated loss expressions of Dab2 were observed in 74.9% and 46.9% in human malignant cancer tissues and cancer cell lines, respectively." (PMID 24772157, 2014). "A total of 395 different human cancer tissues and 32 cancer cell lines were utilized to analyze the expression loss of Dab2 by immunohistochemistry or western blot analysis." (PMID 24772157, 2014). "Frequent loss expression of Dab2 was observed in various human cancers tissues: The immunostained percentage of Dab2 expression were detected in five different kinds of human cancer tissues." (PMID 24772157, 2014). "In conclusion, frequent loss expressions of Dab2 are common in human malignant cancer tissues, and significantly correlated with the promoter hypermethylation." (PMID 24772157, 2014). "DAB2 expression has also been associated with patient outcome in various cancers." (PMID 36614139, 2022). "Together these findings indicate that methylation may be responsible for loss of DAB2 expression in some cancers." (PMID 36614139, 2022). "On the other hand, restoring normal Dab2 expression in Dab2-deficient cancer cells could normalize receptor recycling and TGF-β depletion." (PMID 24638085, 2014). "We hypothesize DAB2 in cancer-associated stroma cells may play a pro-tumorigenic role." (PMID 37815603, 2023). "Consistent with its documented role in various cancers, our analysis revealed a significant downregulation of DAB2 in BC tissues, especially in TNBC." (PMID 40565366, 2025). "Disabled homolog 2 [or DAB adaptor protein 2] (DAB2) is a protein-coding gene that is often deleted or silenced in several human cancer cells." (PMID 38350879, 2024). "DAB2 is an endocytic adaptor protein involved in clathrin mediated endocytosis and is frequently downregulated in cancer." (PMID 37815603, 2023). "Correlation between RepID and DAB2 expression was examined in the Cancer Cell Line Encyclopedia (CCLE) through the CellMinerCDB portal." (PMID 37461562, 2023). "Downregulation of DAB2 expression has been observed in cancers of the breast, placenta, lung, esophagus, cervix, stomach, prostate and nasopharynx." (PMID 37815603, 2023). "This highlights a potential need to explore DAB2 inhibitors in combination with PD-L inhibitors in treating advanced staged cancers." (PMID 36614139, 2022). "DAB2 is mainly expressed in the ovary, brain, kidney and intestine and its downregulation has been observed in cancers including those of the ovary, breast, lung, bladder, prostate, cervix and stomach." (PMID 36614139, 2022). "This review will discuss the role of DAB2 in regulating these key pathways and the resulting effects on cancer progression." (PMID 36614139, 2022).
cancer (continued). "LRP2/megalin was one of the first endocytic cargos identified for the Dab2 adaptor and has been found related to poor prognosis in various cancer." (PMID 35975176, 2022). "Another interesting mechanism through which TAMs cooperate to increase cancer malignant potential involves the protein DAB2 (disabled homolog 2)." (PMID 33143050, 2020). "We identified only networks involving DAB2 related to biological damage and abnormalities, connective tissue disorders, and cancer from these 22 networks." (PMID 31968685, 2020). "Activating mutations of RAS and RAF, and inactivation/repression of endogenous regulators of RAS such as RASSF1 and DAB2 are common in many cancers including HCC." (PMID 32807134, 2020). "This in vitro research showed evidence that DAB2 knock-down can inhibit cancer migration in UM-UC-3 cells and T24, and cancer invasion in J82 and T24." (PMID 31968685, 2020). "Disabled homolog 2 (DAB2) participates in modulation of cancer progression by targeting a number of molecular pathways such as Akt and ERK1/2." (PMID 32612456, 2020). "We semi-quantified DAB2 expression levels in cancer and stromal cells adjacent to the cancerous area separately." (PMID 31968685, 2020). "Epigenetic and transcriptional mechanisms in Dab2 mRNA decline have been reported in cancer cells, including miRNA." (PMID 30873168, 2019). "To date, Dab2 expression has been reported to be reduced or lost in many additional cancer types, including colon, prostate, esophageal, nasopharyngeal, and head and neck." (PMID 27933291, 2016). "Dab2 is a multifunctional adapter protein which is frequently under-expressed in a variety of cancers." (PMID 24638085, 2014). "Unfortunately, some weaknesses of current researches on Dab2 in cancer cell lines are identified in this meta study." (PMID 24772157, 2014). "Decreased expression of DAB2 has been demonstrated in several cancers including ovarian, breast, prostate, oesophagus, urinary bladder, colon and choriocarcinoma." (PMID 20525238, 2010). "Human Disabled-2 (DAB2), is a multi-function signalling molecule that it is frequently down-regulated in human cancers." (PMID 20525238, 2010). "More specifically, in this core interaction network, ceRNAs such as GALNT7, KLF9, and DAB2 and miRNAs like miR-106a/b-5p, miR-20a-5p, and miR-519d-3p may have potential as common targets in the three critical cancers." (PMID 38627780, 2024). "On the other hand, our analysis showed that the GALNT7, KLF9, and DAB2 genes may be particularly critical as ceRNAs in three cancer tissues." (PMID 38627780, 2024). "The results of the study revealed that the miRNA:ceRNA interaction consisting of 63 genes and 165 miRNAs is common to all three cancer tissues and that the GALNT7, KLF9 and DAB2 genes may be involved in critical ceRNA interactions in all three cancer tissues." (PMID 38627780, 2024). "Altogether, our results imply that RepID may transcriptionally repress DAB2 expression in some cancer cells." (PMID 37461562, 2023). "The possibility of the pharmacological modulation of DAB2 gene expression and/or DAB2 function in human cancer might provide an opportunity to suppress the proliferation of malignant cells." (PMID 37510211, 2023). "In silico analyses of cancer cell lines from the Cancer Cell Line Encyclopedia (CCLE) via the Cellminer database showed that the expression of RepID transcripts negatively correlates with DAB2 expression." (PMID 37461562, 2023). "Furthermore, it will explore recent findings which suggest DAB2 has a more complex role in cancer than initially thought." (PMID 36614139, 2022). "Targeting miRNAs in cancers and subsequent re-expression of DAB2 may be a suitable co-treatment with other current treatment strategies." (PMID 36614139, 2022). "A greater understanding of functional role of DAB2 in the TME may highlight potential treatment strategies to target DAB2 in cancer." (PMID 36614139, 2022).